ALDH2 (aldehyde dehydrogenase 2 family member)
Diseases named in the same sentence as ALDH2 in open-access papers (continued):
Sharing a sentence is not in itself a finding about the gene and the disease.
squamous cell carcinoma (5 papers, 2017 to 2024). A carcinoma arising from squamous epithelial cells. "Two variants of DPYD (rs190771411 and rs200562975) and a variant of ALDH2 (rs568781254) were associated with an increased risk of squamous cell carcinoma compared to adenocarcinoma in the dominant model (P < 0.05)." (PMID 36289279, 2022). "Inactive ALDH2 has been reported as a strong risk factor for squamous cell carcinoma of the upper aerodigestive tract in East Asian drinkers." (PMID 34310648, 2021). "Alcohol consumption increases blood and salivary acetaldehyde levels, especially in individuals with ALDH2 polymorphisms, which are highly associated with the risk of squamous cell carcinomas in the upper aerodigestive tract." (PMID 28891965, 2017). "In the present study, the ALDH2 (rs568781254) or DPYD variants (rs190771411 and rs200562975) were associated with an increased risk of squamous cell carcinoma patients compared to adenocarcinoma." (PMID 36289279, 2022). "The cohort consisted of 105 cases, including 64 cases with adenocarcinoma and 30 cases with squamous cell carcinoma, 49 of whom were ALDH2*2 carriers." (PMID 34022841, 2021). "However, due to the low frequency of the minor allele of the variants (MAF of 0.0029 for ALDH2 and MAF of 0.0014 for DPYD), these were not large enough to detect an association with squamous cell carcinoma." (PMID 36289279, 2022).
alcoholic fatty liver disease (4 papers, 2018 to 2025). Lipid infiltration of the hepatic parenchymal cells that is due to alcohol abuse. "We demonstrated that ALDH2 was downregulated in HBV-infected livers and that HBx induced ALDH2 ubiquitin-dependent degradation to enhance alcoholic steatohepatitis." (PMID 36875742, 2023). "Our study demonstrated that HBx-induced ubiquitin-dependent degradation of mitochondrial ALDH2 aggravates alcoholic steatohepatitis." (PMID 36875742, 2023). "Further studies will be necessary to clarify whether the ALDH2 recombinant protein might ameliorate alcoholic fatty liver disease." (PMID 29352167, 2018). "However, we didn’t verify the effect of ALDH2 recombinant protein on mice with alcoholic fatty liver disease." (PMID 29352167, 2018). "In the AM group with long-term ethanol intake, the increased ALDH2 protein level may reflect an attempt by the liver to upregulate ALDH2 expression to cope with acetaldehyde generated during ethanol metabolism in the progression of alcoholic fatty liver disease." (PMID 40433307, 2025).
AMeD syndrome (4 papers, 2022 to 2025). "Inherited mutations in the FA-detoxifying enzymes ADH5 and ALDH2 genes lead to FA overload in the severe multisystem AMeD syndrome." (PMID 38894680, 2024). "AMeD syndrome is characterized by aplastic anemia, mental retardation, short stature, and microcephaly and is caused by digenic mutations in the aldehyde dehydrogenase 2 (ALDH2) and alcohol dehydrogenase 5 (ADH5) genes." (PMID 39211293, 2024). "This indicates that early diagnosis and treatment is important in AMeD syndrome with heterozygous or compound heterozygous ADH5 and ALDH2." (PMID 39211293, 2024).
Cerebral ischemia (4 papers, 2014 to 2020). Restriction of arterial blood supply to the brain associated with insufficient oxygenation to support the metabolic requirements of the tissue. "In summary, we focused on the relationship between brain ischemia and ALDH2 expression, and aimed to seek out the underlying molecular mechanism of ALDH2-induced neuroprotection." (PMID 32210721, 2020). "ALDH2-deficient rodents displayed myocardial or brain ischemia exacerbation, and ALDH2 activation conferred cardio- and neuro-protective properties." (PMID 26599441, 2015). "Cerebral ischemia reperfusion injury significantly down-regulated the expression of ALDH2, resulting in the activated JNK pathway." (PMID 32210721, 2020). "Increased levels of the potential ALDH2 substrate 4-hydroxynonenal (4-HNE) are involved in myocardial/cerebral ischemia accompanied by a high level of oxidative stress." (PMID 25313998, 2014). "In addition, focal cerebral ischemia-reperfusion injury resulted in increased mitochondrial permeability transition pore (mPTP) opening, which was usually at normal levels after ALDH2 overexpression." (PMID 32210721, 2020). "Collectively, ALDH2 overexpression led to a significant reduction in mitochondria-related apoptosis via JNK-mediated caspase-3 activation and transcription in both in vitro and in vivo cerebral ischemia models." (PMID 32210721, 2020).
cognitive decline (4 papers, 2019 to 2024). "Given that formaldehyde is a substrate of ALDH2, the association between urinary formaldehyde concentration and cognitive decline suggests a reasonable link between the rs671 variant and MCI." (PMID 39401906, 2024). "In animal models with low ALDH2, similar to rs671 carriers, Alzheimer’s disease-like pathological findings are observed, including cognitive decline, increases in amyloid protein, and tau protein phosphorylation." (PMID 39401906, 2024). "Mapping of GWAS results identified genes that have been previously associated with cognitive decline including STAU1, SEMF3A, IP6K1, MST1, the ATNX2/BRAP locus, ALDH2 and DDX27, where a likely functional missense variant is highly associated." (PMID 35052462, 2022). "Human ALDH2 mutation also increases the risk for late-onset AD45 and induces cognitive decline in diabetic patients." (PMID 31815201, 2019). "This study explored the decline in cognitive function in patients with different molecular types of ALDH2 after chemotherapy and found that patients with rs671_GG, rs886205_GG, rs4648328_CC, and rs4767944_TT were more likely to have cognitive decline after chemotherapy." (PMID 36200595, 2023).
COVID-19 (4 papers, 2022 to 2024). A disease caused by infection with severe acute respiratory syndrome coronavirus 2. "Subsequently, we observed a lower susceptibility to COVID-19 in individuals carrying the ALDH2 rs671 variant through a web-based retrospective survey." (PMID 39340045, 2024). "Our study indicated for the first time that the variant allele of ALDH2, rs671, is associated with the attenuated immunogenicity of COVID-19 mRNA vaccines." (PMID 35891198, 2022). "Our study indicated for the first time that the variant allele of ALDH2, rs671, which is prevalent in East Asians, is associated with the attenuated immunogenicity of the COVID-19 mRNA vaccine, especially after administration of the second dose." (PMID 35891198, 2022). "A comparison of the proteins in COVID versus ICU-ARDS and normal controls from tryptic or optional phospho/tryptic peptides showed that CYTB, ND5, MRPL37 and ALDH2 were the most specifically elevated mitochondrial proteins in COVID-19 plasma." (PMID 37031181, 2023). "Reduced ALDH2 activity may favor the development and maintenance of COVID-19-specific memory T cells." (PMID 39340045, 2024). "Therefore, the present study aimed to investigate the immune response in a Japanese population, before and after the administration of the COVID-19 vaccination, with the hypothesis that there is an inverse relationship between ALDH2 rs671 and antibody production." (PMID 35891198, 2022).
dependence (4 papers, 2015 to 2025). "Drugs aimed at ERBB2, FCGR3A, and FLT3 are primarily used in treating various cancers and benign tumors, while ALDH2 is targeted in therapies for a range of systemic diseases, notably cancer and substance dependence." (PMID 40868097, 2025).
diabetic retinopathy (4 papers, 2013 to 2020). "The present study aimed to confirm the association between the inactive ALDH2*2 allele and diabetic retinopathy (DR)." (PMID 24028448, 2013). "Furthermore, studies also found that diabetic retinopathy development is associated with the ALDH2 polymorphism." (PMID 28208752, 2017). "Interestingly, diabetic retinopathy (DR) was also closely related to ALDH2 polymorphisms." (PMID 33411685, 2020). "Simultaneously, our previous animal experiments have also shown that ALDH2 could play a certain role in aged diabetic retinopathy and retinitis pigmentosa (RP)." (PMID 33411685, 2020). "Up to the present, several studies have demonstrated the relationship between ALDH2 rs671, T2DM, and diabetic retinopathy (DR)." (PMID 28208752, 2017).
Headache (4 papers, 2012 to 2025). Cephalgia, or pain sensed in various parts of the head, not confined to the area of distribution of any nerve. "People with ALDH2 deficiency and headaches, including migraine, consumed alcohol statistically significantly less often than those with properly functioning ALDH2, and additionally, patients with migraine consumed alcohol less often than patients with TTH." (PMID 41305669, 2025). "Some alcohol consumers exhibit flushing and experience headaches, and this is attributed to a dysfunctional ALDH2 variant, the enzyme that metabolizes acetaldehyde, allowing it to accumulate." (PMID 37985790, 2023). "The replies to the flushing questionnaire revealed that 45.6% of the 2,577 headache sufferers (men/women: 48.3%/43.8%) were current or past flushers, and they were predicted to have inactive ALDH2." (PMID 22234728, 2012).
Hepatitis (4 papers, 2017 to 2022). Inflammation of the liver. "Therefore, individuals with the dominant inactive ALDH2*2 gene should be informed of their higher risk for liver inflammation and fibrosis after moderate or heavy drinking." (PMID 32140062, 2020). "Acetaldehyde levels increased in ALDH2 (-) mice when exposed to alcohol, and hepatitis was attenuated in ALDH2 (-) mice compared to wild-type mice." (PMID 35185542, 2021).
hypopharyngeal cancer (4 papers, 2017 to 2023). Carcinoma, predominantly squamous cell, arising from the epithelial cells of the hypopharynx. "IHC and western blot showed that ALDH2 is downregulated in the oral cavity, hypopharyngeal cancers, and well-differentiated carcinoma." (PMID 37476181, 2023). "ALDH2 gene was also expressed at low levels in patients with oral cavity cancers or hypopharynx cancers." (PMID 28841898, 2017). "ALDH2 gene was also expressed in low levels in patients with oral cavity cancers or hypopharynx cancers." (PMID 28841898, 2017). "Western blot analysis revealed that the ALDH2 level of hypopharyngeal cancer tissues tends to be lower than those in paired non-cancer tissues (n = 3), suggesting the trend is consistent with those from the omic prediction from the HNSC/TCGA cohort." (PMID 37476181, 2023).
liver cirrhosis (4 papers, 2014 to 2025). "However, because of the associated unpleasant symptoms, alcohol consumption tends to be self-limited; therefore, the low-activity ALDH2 variant is associated with a reduced risk of liver cirrhosis (OR = 0.78, 95% CI: 0.61–0.99)." (PMID 40943250, 2025).
lymph node metastasis (4 papers, 2022 to 2025). "The IHC results also showed that the expression of the IGSF9, PRDM16, and ALDH2 proteins was significantly associated with a higher level of lymph node metastasis." (PMID 35013309, 2022). "Aldehyde dehydrogenase 2 family member (ALDH2) and nitric oxide synthase 1 (NOS1) have been linked to lymph node metastasis and bone metastasis in BRCA, respectively." (PMID 41278297, 2025). "Reduced copy numbers of IGSF9 and PRDM16 and the increased copy number of ALDH2 were intricately intertwined with lymph node metastasis and reduced survival rates in IMPC patients." (PMID 38181281, 2024). "The correlation analyses showed that IGSF9 and PRDM16 protein levels inversely correlated with lymph node metastasis (IGSF9, R = −0.32, P < 0.01; PRDM16, R = −0.336, P < 0.01), while ALDH2 protein expression positively correlated with lymph node metastasis (ALDH2, R = 0.262, P < 0.05)." (PMID 35013309, 2022).
non-alcoholic fatty liver disease (4 papers, 2020 to 2025). "Additionally, DEA also exhibited protective effects against non-alcoholic fatty liver disease (NAFLD) through activating ALDH2 and accelerating the elimination of ROS and harmful aldehydes." (PMID 36678511, 2022).
oral cavity cancer (4 papers, 2016 to 2023). A primary or metastatic malignant neoplasm involving the oral cavity. "The univariate analysis demonstrated that early T stages (T1/T2) were significantly correlated to high ALDH2 levels in both oral cavity cancer (n = 300, P = 1.7×10-3) and non-oral cavity cancer (n = 190, P = 4.89×10-2, student t-test) groups." (PMID 37476181, 2023).
pulmonary fibrosis (4 papers, 2022 to 2025). Chronic progressive interstitial lung disorder characterized by the replacement of the lung tissue by connective tissue, leading to progressive dyspnea, respiratory failure, or right heart failure. "Previously, it was reported that the overexpression of ALDH2 alleviated excessive ECM deposition in primary idiopathic pulmonary fibrosis (IPF)-derived lung fibroblasts." (PMID 37443810, 2023). "Decreased ALDH2 expression was noted in patients with idiopathic pulmonary fibrosis and in mice with bleomycin-induced pulmonary fibrosis, along with evident impairment of mitophagy, which is positively correlated with fibroblast activation and abnormal extracellular matrix accumulation." (PMID 40968356, 2025). "Correspondingly, pulmonary fibrosis expressed by trichrome staining and western blot analysis of alpha-smooth muscle actin (α-SMA) and fibronectin were both aggravated by the knockout of ALDH2." (PMID 35770049, 2022).
viral hepatitis (4 papers, 2019 to 2024). An acute or chronic inflammation of the liver parenchyma caused by viruses. "Additionally, ALDH2*2 is reported to increase the risk for leprosy, whereas viral hepatitis is mild in ALDH2*2 carriers, likely due to the alleviation of inflammation by the presence of aldehydes." (PMID 34022841, 2021).
acute coronary syndrome (3 papers, 2018 to 2024). Signs and symptoms related to acute ischemia of the myocardium secondary to coronary artery disease. "The ALDH2 rs671 (A) allele was associated with high levels of hs-CRP in both acute coronary syndrome patients and control subjects." (PMID 39290715, 2024). "Aldehyde dehydrogenase 2 (ALDH2) Glu504Lys variant was an independent risk factor for acute coronary syndrome (ACS)." (PMID 29441687, 2018).
acute myeloid leukemia (3 papers, 2021 to 2025). Acute myeloid leukemia (AML) is a group of neoplasms arising from precursor cells committed to the myeloid cell-line differentiation. "Therefore, our results help strengthen the connection between the function of the FA pathway and the role of ALDH2, also consistent with a recent study in Acute Myeloid Leukemia." (PMID 34454516, 2021).
alcohol-related polyneuropathy (3 papers, 2019 to 2024). "Masaki and colleagues investigated the role of Glu-487→Lys mutation (single nucleotide polymorphism) of the aldehyde dehydrogenase-2 (ALDH2) in alcohol-related polyneuropathy in a cohort in Japan." (PMID 30467601, 2019). "A previous study clarified the role of acetaldehyde in alcoholic brain injury by transgenic overexpression of ALDH2 in mitochondria, enabling a better understanding of mechanisms of alcoholic neuropathy." (PMID 36743287, 2022).
angina (3 papers, 2018 to 2025). "This study reveals significant regional differences in ALDH2 rs671 polymorphism and its association with lifestyle factors in angina pectoris patients across China." (PMID 40979589, 2025). "The aggregate data (Geographical Distribution of ALDH2 rs671 Polymorphism in Chinese angina pectoris Patients), supporting the findings of this study, are available within this article." (PMID 40979589, 2025). "The ALDH2 variant reduces enzymatic activation of nitroglycerin, a key drug used for angina symptom relief, leading to decreased vasodilatory effects." (PMID 40979589, 2025). "In addition to examining the geographical distribution of ALDH2 polymorphisms, it is essential to explore how these genetic variations interact with clinical and lifestyle factors in angina pectoris patients." (PMID 40979589, 2025). "This gap in research is particularly important because ALDH2 plays a crucial role in the metabolism of nitroglycerin, a key medication used to relieve angina symptoms." (PMID 40979589, 2025). "This study aims to fill this gap by examining the genotypic and allelic frequencies of ALDH2 in angina pectoris patients from three geographically distinct regions—northern, eastern, and southern China." (PMID 40979589, 2025). "These pharmacogenetic findings underscore the importance of considering ALDH2 genotype when prescribing nitrate therapy for angina pectoris." (PMID 40979589, 2025). "By the integration of the DEGs of healthy/MI and unstable angina/MI, the potential targets of Yixinyin for the treatment of MI (ALDH2, C5AR1, CFOS, IL1B, TLR2, TRXR1) have been obtained." (PMID 34799616, 2021). "The G-to-A mutation at the ALDH2 rs671 locus results in reduced or absent enzyme activity, significantly impairing the conversion of nitroglycerin into nitric oxide, which is necessary for vasodilation and pain relief in angina patients." (PMID 40979589, 2025). "Despite this known variation in the general population, the distribution of ALDH2 genotypes among patients with angina pectoris had not been thoroughly investigated before this study." (PMID 40979589, 2025).
bipolar disorder (3 papers, 2018 to 2024). A disorder of the brain that causes unusual shifts in mood, energy, activity levels and the ability to carry out day-to-day tasks. "The possible association between ALDH2 polymorphisms and comorbidity in bipolar disorders on cognitive profiles needs further investigation." (PMID 29425204, 2018). "They found that a significant associations between ALDH2*1/*1 genotype and the improvement of cognitive function in patients with bipolar disorder in a one-year follow up." (PMID 29425204, 2018). "In addition, a possible protective factor of ALDH2*1/*2 and ALDH2*2/*2 is for some of memory functions in the BP-II−AD from the effect of bipolar disorder on decreasing memory functions." (PMID 29425204, 2018).
chronic kidney disease (3 papers, 2018 to 2026). Impairment of the renal function secondary to chronic kidney damage persisting for three or more months. "The Aldehyde dehydrogenase 2 (ALDH2) rs671 polymorphism, a common variant that impairs aldehyde detoxification, has been linked to cardiovascular disease, but its role in chronic kidney disease (CKD) remains unclear." (PMID 41834010, 2026). "The SNP rs671 in ALDH2 also affects acute rejection after kidney transplantation and drug metabolism in end-stage renal disease patients." (PMID 29558500, 2018).
chronic obstructive pulmonary disease (3 papers, 2017 to 2025). A chronic and progressive lung disorder characterized by the loss of elasticity of the bronchial tree and the air sacs, destruction of the air sacs wall, thickening of the bronchial wall, and mucous accumulation in the bronchial tree. "Moreover, the presence of ALDH2*2 (an inactive allele of ALDH2) has been associated with an increased risk of developing smoking-associated chronic airway obstruction in a Japanese population." (PMID 36672235, 2023). "ALDH2 concentration is prominently elevated in the bronchoalveolar lavage fluid of patients with chronic obstructive pulmonary disease (COPD)." (PMID 28431562, 2017).
chronic pancreatitis (3 papers, 2013 to 2023). A chronic inflammatory process causing damage and fibrosis of the pancreatic parenchyma. "Since, ALDH2 enzyme is the main form of aldehyde dehydrogenase responsible for acetaldehyde oxidation and polymorphism at its locus has been shown to be associated with chronic pancreatitis, we also investigated ALDH2." (PMID 26734614, 2015). "ALDH3B1, ENO1, ALDH2, GAPDH, and LDHC had significant differences among grades, while ALDH3B1, PKM, and ALDH3B2 differed among chronic pancreatitis histories." (PMID 36814901, 2023).